TNF (tumor necrosis factor)
Diseases named in the same sentence as TNF in open-access papers (continued):
Sharing a sentence is not in itself a finding about the gene and the disease.
infection (continued). "Patients with LTBI who are living in an endemic area, undergoing renal dialysis, had organ transplantation or receiving anti-cancer agents such as tumor necrosis factor-alpha blockers (TNF-α blockers) drugs are at a significantly higher risk for reactivation of the infection." (PMID 36600835, 2023). "Upregulation of IL-6 and TNF-α expression may be attributed to tissue damage caused by infection or oxidative stress." (PMID 37711631, 2023). "abundance and its coexistence with other intestinal protozoa were associated with increase of IFABP2 and TNF-α serum levels, thus suggesting a relation between infection by intestinal protozoa and the potential damage of the intestinal epithelium and inflammation in patients with RA." (PMID 35492365, 2022). "The most common serious adverse event associated with TNF inhibitors is an infection." (PMID 36430392, 2022). "In the case of infection, immune cells release tumor necrosis factor (TNF-α), IL-1, IL-6, IL-8 and other signaling molecules, causing a systemic inflammatory response and stimulating different tissues (kidney, adipose tissue, lung, and liver) to secrete PCT, and their blood concentrations increase." (PMID 35462904, 2022). "When genetically susceptible individuals are exposed to infection, stress or trauma, cutaneous dendritic cells are activated to produce tumor necrosis factor (TNF)-α and interleukin (IL)-23, which subsequently stimulate the proliferation and differentiation of proinflammatory T cells." (PMID 35927231, 2022). "Few patients have a mild increase in TNF-α level after induction chemotherapy, indicating multifactorial causes such as infection and inflammation that may lead to an increase in TNF-α level and not solely due to disease burden." (PMID 35547942, 2022). "Kyoto Encyclopedia of Genes and Genomes analysis revealed that the upregulated genes in TP-infected macrophages were enriched in cytokine production and inflammatory signaling pathways such as the TNF signaling pathway, along with pathways associated with infection, and endocytosis." (PMID 35444649, 2022). "The Th1 profile produces cytokines such as interferon-gamma (IFN-γ), tumor necrosis factor (TNF), and interleukin 2 (IL-2), which are associated with the control of infection by macrophages, the production of nitric oxide (NO), and the consequent destruction of intracellular parasites." (PMID 35844611, 2022). "ILC1s are the major producers of IFN-γ and TNF-α in the gut during Toxoplasma gondii infection, and T-bet-deficient mice that lack ILC1s fail to control parasite replication during the early stage of infection." (PMID 35163778, 2022). "TNF-α levels are linked to the severity of infection-induced pulmonary damage." (PMID 35669119, 2022). "Likely, the elevated plasma IL-10 (optimal threshold >11.59 pg/mL) inhibits antigen presentation, decreasing ex vivo LPS-stimulated TNF-α production capacity (optimal threshold < 505.8 pg/mL) leaving the individual highly susceptible to infections by decreasing T cell immunity." (PMID 35958579, 2022). "Glycyrol may also regulate TNF to reduce cell damage and death thereby alleviating damage from the inflammatory response caused by infection." (PMID 36506032, 2022). "Past studies place promoter polymorphisms of TNF-α in inflammatory and infection-prone conditions." (PMID 36672608, 2022). "Furthermore, we identify an alternate inflammatory BV signature characterized by elevated TNF-α/MIP-1β ratio that is prospectively associated with progression of incident infections to CIN2 + (OR = 2.81, 95% CI: 1.62-5.42)." (PMID 35017496, 2022). "However, the risk of overall and opportunistic infections seems to increase with anti-TNF treatment." (PMID 35140875, 2022). "However, given the important role of TNF-α in host defense against infection, anti-TNF therapy increases susceptibility to infection, such as Mycobacterium tuberculosis and atypicalum." (PMID 35990692, 2022).
infection (continued). "Evidence is emerging that antibody concentrations decrease more rapidly in patients with IBD treated with anti-TNF drugs and that these patients are at greater risk of breakthrough infection following two doses of vaccine than patients with IBD treated with vedolizumab." (PMID 36088954, 2022). "The various activities of the cytokine have been investigated in models of inflammation, cancer, autoimmunity, and infection using gene-deficient mice, and more recently, in tissue-specific gene-deficient mouse models unable to express TNF in either macrophages or T cells." (PMID 36358688, 2022). "This may be due to evidence in favor of abatacept, compared with IL6 receptor inhibitors and TNF inhibitors, regarding the risk of severe infection." (PMID 35945556, 2022). "Like IL-17A and TNFα, IL-1α and IL-1β are associated with barrier tissue chronic inflammatory diseases and targeted in treatment, and inhibition of these mediators also increases risk of infection." (PMID 36591258, 2022). "Patients with NPC1 suffer from a severe life-limiting disease, the potential risks of TNF therapy (demyelination and increased infection susceptibility) must be balanced against the improvement in quality of life due to effective IBD therapy and symptom control." (PMID 35694196, 2022). "Interestingly, a retrospective Medicare and Medicaid cohort study reported that the risk of serious infections with anti-TNF and with long-term steroid treatment was similar, but a higher mortality with steroids was observed." (PMID 35160280, 2022). "Remarkably, high levels of TNF were associated with surgical site infection and worsening of the mucosal epithelial barrier function, while TNF inhibitor treatment was shown to reduce surgical site infection." (PMID 36466891, 2022). "An excessive release of inflammatory factors, including IL-6, IL-12, IL-1β, and TNF-α, from immune disorders caused severe apoptotic damage to immune organs, which was consistent with MG-Rlow infection-induced damage to the spleen, thymus, and bursa of fasciola." (PMID 36139393, 2022). "In addition, since multiple studies have demonstrated that patients receiving biologics are at high risk of infections, we investigated the infection rate associated with TNF-α inhibitors." (PMID 36079718, 2022). "Then, potential host-directed treatments that could mitigate or treat TNF inhibitor-associated infections alongside antibiotics will be reviewed with a focus on metformin." (PMID 36159650, 2022). "Anti-TNF therapy may cause an increase in active tuberculosis, other granulomatous diseases, and serious infections." (PMID 36161620, 2022). "The infection with the influenza virus causes acute inflammation via a direct invasion into the CNS, resulting in the excessive production and action of proinflammatory cytokines including TNF-α and interleukin (IL)-6." (PMID 35326323, 2022). "Hyper production of IFN-γ by Th1 cells during infection will activate macrophages and TNF-α as well as chemokines, which might finally cause tissue inflammation and damage." (PMID 36059554, 2022). "In orchiectomized mice, MC showed a retarded activation pattern, associated with slower degranulation and weaker TNF-α, histamine, and tryptase staining in response to the infection with Leishmania mexicana combined with vector-salivary proteins, as compared to sham mice." (PMID 35456073, 2022). "In accordance with these reports and our finding of higher IFNγ levels in highly susceptible BALB/c mice, we tested if blocking IFNγ and TNF might reduce disease severity after maVie16 infection." (PMID 35023830, 2022). "Furthermore, the combined inhibition of IFN‐γ and TNF‐α during an acute infection reduced the mortality associated with SARS‐CoV‐2 infection in a mouse model." (PMID 34141432, 2021). "However, the prior anti-TNF experience was also associated with increased incidence of infection and serious infection during tocilizumab therapy." (PMID 33930048, 2021).
infection (continued). "However, immunosuppression, and a corresponding increase in infection risk, is a danger of over-treatment with TNF inhibitors and other targeted therapies." (PMID 33535498, 2021). "Furthermore, the results of enzyme-linked immunosorbent assays (ELISAs) showed that infection with the E. faecalis WT strain notably activated the secretion of TNF-α from RAW264.7 cells." (PMID 34491082, 2021). "However, long-term use increases the risk of infection and tumors for their systemic inhibition of TNF-α, which disrupts the regular physiological function of this molecular." (PMID 34627365, 2021). "However, anti-TNF-α therapy has been ineffective in more than 40% of patients and is associated with adverse effects such as the increased risk of infection, mainly of Mycobacterium tuberculosis (MTB)." (PMID 34025650, 2021). "There are also limited data suggesting that patients treated with TNF inhibitors may have an increased risk of hospitalisation due to infection compared with patients treated with abatacept." (PMID 33535498, 2021). "This L. casei associated increased susceptibility to infection may be related to deactivation of TNF-α dependent Th2 effector responses against T. muris due to the strong inhibitory effect of L. casei on this cytokine." (PMID 33897683, 2021). "Several investigators have reported that L. fermentum is an antimicrobial probiotic that can reduce the risk of infection and has the ability to reduce concentrations of pro-inflammatory factors, ameliorate colon cells, and reduce TNF-α levels in in vivo experiments." (PMID 34489374, 2021). "In addition, a random-effects model was used to calculate the pooled odds ratio, and Forest plots were constructed to determine the risk of infections and cancer following the use of anti-TNF treatment." (PMID 34790122, 2021). "High levels of IL-5 and TNF suggested that the children may be suffering from morbidity associated with S. mansoni, especially due to the fact that most children had heavy infection intensities before treatment." (PMID 34239575, 2021). "Moreover, TNF-α released from inflammatory monocytes assists C. parvum in loss of intestinal barrier to propagate the infection." (PMID 34946170, 2021). "Interestingly, counts of Enterococcus were negatively correlated with levels of pro-inflammatory markers such as TNFα and MIP1α, an odd finding considering Enterococci have been associated with risk for infection in preterm neonates." (PMID 33479274, 2021). "However, an increased number of M1 phenotype macrophages, which are induced by various pathogenic factors such as tumor necrosis factor, interferon-γ, and pathogen infection, have been associated with some abnormal pregnancy complications." (PMID 33897665, 2021). "Besides this deficiency, diabetic wounds also show a shortage in the production of tumor necrosis factor-α (TNF-α), making wounds more susceptible to infection in the initial phase of wound healing." (PMID 34769092, 2021). "Blocking cytokines such as TNF- α may reduce inflammation but also renders the host susceptible to infection by silencing the danger signals, which are necessary for adequate immune cell activation and maybe even to cancer." (PMID 33692997, 2021). "However, infection with Lm and stimulation with TNF strongly increased association of OTUB1 with c-IAP1 and deubiquitination of K48-linked polyubiquitin chains from c-IAP1, thereby reducing its degradation." (PMID 33712742, 2021). "Stimulation of the inflammatory response, either to an underlying disease or infection, results in abundant expression of cytokines, like tumor necrosis factor alpha (TNFα) and interleukin 6 (IL6), which lead to endothelial activation of adhesion molecules and further chemokine production." (PMID 34025658, 2021).
infection (continued). "Although inflammatory factors can produce adaptive behavioral response and promote energy conservation to fight infection or recover from injury, excessive proinflammatory factors (such as TNF-α and IL-1β) will cause damage to the body and cause inflammation-related diseases." (PMID 34630124, 2021). "The contribution of excessive TNFα production was further emphasized by using TNFRp55-/- mice that exhibited a 90% survival rate due to the disruption of the TNFα−stimulation pathway resulting in diminished pathology associated with WA1 infection." (PMID 34414129, 2021). "In conclusion, we show that combining Mtb antigens with various functional, spatial and temporal availability during infection we can induce inflammatory cytokines (IL-17 and TNFα) that can impact bacterial growth, but which also are also associated with weight loss upon aerosol infection." (PMID 34070048, 2021). "Pro-inflammatory cytokines, such as IL-1β, IL-6, and TNF-α, released by tumor itself or immune cells following infection or tissue injury caused by chemotherapy, surgery, or radiation can signal to the CNS, leading to symptoms of distressing fatigue and other behavioral changes." (PMID 34122094, 2021). "The high level of IFN-γ and TNF-α may be a reflection of inflamm-aging in elderly RMs and may have a promoting effect on lung lesions caused by infection." (PMID 34471088, 2021). "In addition, the pretreatment with Ab extract leads to a complete control of bacteremia 24 h post infection, associated with an augment in NO, and a significant decrease in IL-1β and TNF-α levels in septic animals." (PMID 32714320, 2020). "Because TNF-α is an important component of the immune response, antagonizing TNF-α may increase the risk of infection, especially in HIV patients." (PMID 32039436, 2020). "TNF signaling was reported to be essential for protective Mabc granuloma formation through IL-8-dependent neutrophil trafficking since TNFR1 deficiency led to increased lethality in ZF Mabc-R infection models." (PMID 32835604, 2020). "Food intake mirrored weight loss: r-TNF-α-dosed mice ate less between 1 and 2 days after infection." (PMID 32071269, 2020). "The level of TNF‐α is an essential cytokine for the host defense, and its depletion by treatment may facilitate the risk of infections or their reactivation." (PMID 32725811, 2020). "Different studies were conducted to evaluate if there was a higher risk of severe infection in those patients treated with anti-TNF therapy, showing a sizeable increase, up to 2-fold, which correlates with the dosage and the association with other immunosuppressive therapies." (PMID 32269571, 2020). "Systemic treatments include synthetic or biologic disease-modifying antirheumatic drugs (DMARDs), such as methotrexate, cyclosporine and TNF-α, IL-17, IL-12/23 and IL-23 inhibitors, which have been associated with increased risk of infection, including respiratory tract viral infection." (PMID 33276686, 2020). "TNF-α and IL-1β both participated in the inflammation in the early stage, and they were associated with activating and recruiting neutrophils to the site of infection." (PMID 32581788, 2020). "Likewise, the application of monoclonal anti-TNFα antibodies has been reportedly associated with aggravated infections." (PMID 33117382, 2020). "Moreover, all of these transcripts and their cognate genes have been implicated in functions related to the infection related pathways (TNF signaling pathway, IL-17 signaling pathway, Th1 and Th2 cell differentiation)." (PMID 33488611, 2020). "However a prolonged use of TNF inhibitors has a few possible side effects like: hepatotoxicity, malignity, greater risk for infection, immunogenicity and cutaneous reactions." (PMID 33193432, 2020). "In these studies, the risk of infection among IBD patients was further enhanced by anti-TNF agents." (PMID 33551798, 2020).
infection (continued). "TNF levels were significantly higher in supernatants from ∆M36-infected cells at 6 hpi, indicating that vICA suppresses death-associated inflammation during infection of myeloid cells." (PMID 33126536, 2020). "CGD patients have a high risk of infection, therefore anti-tumor necrosis factor (TNF) alpha is contraindicated as it may increase this risk." (PMID 33553075, 2020). "In this context, it is however noteworthy that the risk of infection in patients receiving TNF blockers could be somewhat influenced by the underlying disease." (PMID 33551798, 2020). "TNF α, IL-6 and IL-12 increases in current depressive episodes underline the systemic nature of the inflammatory status, showing some similarity to the immune reaction to an active infection." (PMID 32113908, 2020). "ADM, as a multiregulatory molecule, could be induced by TNF-α under infection and inflammation and has been implicated in the host anti-microbe response by the interaction with complex receptor systems." (PMID 33281794, 2020). "Only microscopic infections at delivery showed a positive association with TNF levels." (PMID 32365058, 2020). "Furthermore, Il22−/− mice succumbed earlier to infection, which was associated with increased local production of TNF-α and IL-1β, reduced IL-1ra, as well as increased lung inflammation." (PMID 32517114, 2020). "TNF activities are widespread but are predominantly pro-inflammatory in early stage immune responses, serving to actively suppress M2 polarization in tumor associated macrophages and infection models." (PMID 32760383, 2020). "According to a Cochrane review, the risk of infection in patients with inflammatory arthritis [IA; including RA, psoriatic arthritis (PsoA) and spondylarthritis (SpA)] is higher under therapy with TNF-blockers than with conventional disease modifying anti-rheumatic drugs (DMARDs) only." (PMID 33154972, 2020). "In our system, an increase in the proportion of CD4+ T cells in spleen cells and the parallel elevation of IL-2, IFN-γ, and TNF-α in serum after 11 days of infection in mice suggested that Th1 immune responses may be caused by early infection by T. pallidum." (PMID 33488577, 2020). "TNF-alpha inhibitors are thought to increase the general risk of infection." (PMID 32600315, 2020). "During infection, pathogen- and damage-associated molecular pattern (PAMPs & DAMPs) molecules activate the innate immune system to produce inflammatory cytokines such as Tumor Necrosis Factor (TNF) and interleukins." (PMID 30700738, 2019). "However, TNF-α has been implicated in the initial events of the infection mediating the disease expression." (PMID 31469834, 2019). "Indeed, during C. burnetii infection TNF deficient mice presented a defect of infection control as for other pathogens such as Listeria monocytogenes or Mycobacterium tuberculosis." (PMID 31749776, 2019). "Moreover, IFN-γ cannot control infection alone and it requires the association of other molecules such as IL-6, IL-1 and the TNF-α." (PMID 31508399, 2019). "Anti-TNF therapy can also enhance risk of infection with M. intracellulare and M. avium pathogens." (PMID 30763316, 2019). "The primary aim of this meta-analysis was to explore whether the TNF-alpha inhibitor therapy leads to an increased risk of infection in JIA children." (PMID 30658717, 2019). "Infection of mice with African trypanosomes (including T. congolense) is associated with high levels of serum proinflammatory cytokines (including IL-12p40, IL-6, and TNF-α) and nitric oxide (NO)." (PMID 31824484, 2019). "Severe infection can trigger production of large amounts of TNF which can cause systemic reactions." (PMID 32148672, 2019). "Treatment with TNFα resulted in the induction of well-known target genes and accordingly a gene ontology (GO) analysis revealed the involvement of these target genes in biological processes associated with infection and immunity." (PMID 31242600, 2019).